ZNF516 (zinc finger protein 516)
Description:
Transcriptional regulator that binds to the promoter and activates the transcription of genes promoting brown adipose tissue (BAT) differentiation. Among brown adipose tissue-specific genes, binds the proximal region of the promoter of the UCP1 gene to activate its transcription and thereby regulate thermogenesis (By similarity). May also play a role in the cellular response to replication stress.
Synonyms: KIAA0222; HsT287
Tractability: PROTAC: UniProt records ubiquitination sites on it; ubiquitination databases record sites on it; its protein half-life has been measured.
Gene: Protein-coding gene on chromosome 18 (76,357,682 to 76,496,132, reverse strand). Ensembl gene ENSG00000101493.
Subcellular location: Nucleus
Subcellular location (Human Protein Atlas): Nucleoplasm; Cytosol
Gene Ontology:
Molecular function: protein binding; cis-regulatory region sequence-specific DNA binding; DNA-binding transcription factor activity, RNA polymerase II-specific; RNA polymerase II cis-regulatory region sequence-specific DNA binding; DNA-binding transcription factor binding
Biological process: adipose tissue development; brown fat cell differentiation; positive regulation of cold-induced thermogenesis; positive regulation of DNA-templated transcription; regulation of DNA-templated transcription; regulation of transcription by RNA polymerase II; response to cold
Cellular component: nucleus
Genetic constraint (gnomAD): Loss-of-function variants: 19 observed, 68.01 expected, observed/expected ratio (o/e) 0.28, 90% interval 0.19 to 0.41. The synonymous counts are far from expectation, so gnomAD's model fits this gene poorly and the ratio says little. Missense variants: 1,678 observed, 1,620.5 expected, observed/expected ratio (o/e) 1.04, 90% interval 0.99 to 1.08. Synonymous variants: 877 observed, 727.87 expected, observed/expected ratio (o/e) 1.2, 90% interval 1.14 to 1.27.
Homologues: Orthologues: chimpanzee ZNF516 (99% identical), macaque ZNF516 (98% identical), guinea pig ZNF516 (83% identical), mouse Zfp516 (82% identical), rat Zfp516 (78% identical), dog ZNF516 (75% identical), pig ZNF516 (73% identical), rabbit ZNF516 (72% identical), tropical clawed frog znf516 (51% identical). Paralogues in human: ZNF536 (24% identical), ZNF217 (20% identical), ZNF219 (13% identical), SALL3 (13% identical), SALL1 (12% identical), HIVEP1 (12% identical), HIVEP3 (12% identical), HIVEP2 (11% identical), RREB1 (10% identical), SALL4 (10% identical), BCL11B (8% identical), BCL11A (8% identical), and 2 more.
Diseases named in the same sentence as ZNF516 in open-access papers:
ZNF516 is named in the same sentence as 9 diseases in open-access papers, as found by Europe PMC text mining. Sharing a sentence is not in itself a finding about the gene and the disease. The quoted sentences say what the papers report.
breast carcinoma (4 papers, 2017 to 2024). "Nevertheless, it is a plausible scenario that loss of ZNF516 expression would lead to the up-regulation of EGFR during breast cancer carcinogenesis." (PMID 28947780, 2017). "Significantly, low expression of ZNF516 is positively associated with advanced pathological staging and poor survival of breast carcinomas." (PMID 28947780, 2017). "In an effort to explore the mechanistic role of ZNF516 in breast cancer carcinogenesis, we cloned the gene encoding for ZNF516 from a human mammary cDNA library." (PMID 28947780, 2017). "Here, analysing genome-wide chromatin associations, the authors show that in breast cancer cells ZNF516 represses EGFR transcription through the interaction with the CtBP/LSD1/CoREST complex." (PMID 28947780, 2017). "Moreover, higher ZNF516 expression is associated with a better relapse-free survival of breast cancer patients of luminal A and even basal-like subtypes." (PMID 28947780, 2017). "It is currently unknown if similar genetic or/and epigenetic abnormalities of ZNF516 also occur in breast cancer, and it is unclear the sequence of the events associated with the aberrant expression of ZNF516 and EGFR." (PMID 28947780, 2017). "LSD1 also suppresses the proliferative and invasive ability of breast cancer cells by interacting with ZNF516-CtBP/CoREST and inhibits breast cancer growth and metastasis in vivo." (PMID 38448424, 2024). "The next pathway, ESR1, which was mutated in breast cancer, received microenvironment factor S100A4 to regulate TF ETS1 and SMAD3 through signaling transduction proteins ZNF516, PIK3R1, IDH1, and AKT1." (PMID 33802957, 2021). "We demonstrate that the ZNF516 inhibits the proliferation and invasive potential of breast cancer cells in vitro and suppresses breast cancer growth and metastasis in vivo." (PMID 28947780, 2017). "Our data indicate that ZNF516 is a transcription repressor and a potential suppressor of EGFR, adding to the understanding of EGFR-related breast carcinogenesis and supporting the pursuit of ZNF516 as a potential therapeutic target for breast cancer." (PMID 28947780, 2017). "We then performed transwell cell invasion and tested the effect of ZNF516 on the invasive potential of breast cancer cells." (PMID 28947780, 2017). "The results showed that ZNF516 overexpression had a significant inhibitory effect on breast cancer cell proliferation, a phenotype that could be rescued by simultaneous overexpression of EGFR." (PMID 28947780, 2017). "Consistently, depletion of ZNF516 promoted breast cancer cell proliferation, an effect that could be abrogated, at least partially, by co-knockdown of EGFR." (PMID 28947780, 2017). "To investigate this hypothesis, we first tested the effect of the ZNF516–CtBP/LSD1/CoREST complex on the proliferation of breast cancer cells in vitro." (PMID 28947780, 2017). "We explore the clinical significance of the ZNF516–CtBP/LSD1/CoREST–EGFR axis in breast carcinomas." (PMID 28947780, 2017). "The identification of EGFR as a target of the ZNF516–CtBP/LSD1/CoREST complex and the well-documented role of EGFR in the development and progression of of various malignancies suggest that the ZNF516–CtBP/LSD1/CoREST complex may also function in breast cancer growth and metastasis." (PMID 28947780, 2017). "A transcription factor, ZNF516, was shown to recruit the CtBP/LSD1/CoREST complex to inhibit the proliferation and invasion of breast cancer cells in vitro and suppress breast cancer growth and metastasis in vivo." (PMID 35687133, 2022). "We demonstrate that the ZNF516–CtBP/LSD1/CoREST complex inhibits the proliferation and invasion of breast cancer cells in vitro and suppresses breast cancer growth and metastasis in vivo." (PMID 28947780, 2017).
breast carcinoma (continued). "In the current study, we found that the expression of ZNF516 is progressively lost during breast cancer progression, and, consistent with our observation that ZNF516 transcriptionally represses EGFR, we showed that the level of ZNF516 expression is negatively correlated with that of EGFR." (PMID 28947780, 2017). "To gain further support of the role of the ZNF516–CtBP/LSD1/CoREST–EGFR axis in the development and progression of breast cancer and to extend our observations to a clinicopathologically relevant context, we first profiled the expression pattern of ZNF516 and EGFR in breast cancer cell lines." (PMID 28947780, 2017). "Nevertheless, our results indicate that ZNF516 is a transcription repressor and a potential suppressor of EGFR, adding to the understanding of EGFR-related breast carcinogenesis and supporting the pursuit of ZNF516 as a potential therapeutic target for breast cancer." (PMID 28947780, 2017). "Furthermore, analysis of published clinical data sets (GSE21653) revealed negative correlations of mRNA levels between ZNF516 and EGFR in different subtypes of breast cancers." (PMID 28947780, 2017).
bladder cancer (1 paper, 2021). "No specific investigations on the ZNF516 repressor in bladder cancer have been published, whereas several investigations suggest that the class IIA histone deacetylase HDAC4 inhibits neoplastic properties of bladder cancer cells." (PMID 34885146, 2021).
congenital aural atresia (1 paper, 2014). "However, deletion of a critical region on 18q23 that includes the ZNF407 gene and two other zinc finger genes (ZNF516 and ZNF236), among other genes, is correlated with congenital aural atresia (CAA), which manifests a subset of phenotypes recognized by the 18q deletion (18q-) syndrome." (PMID 24907849, 2014).
developmental delays (1 paper, 2022). "The region related to developmental delays and abnormal cerebral white matter development is 18q22.3q23, and the possible related pathogenic genes are ZNF236, ZNF516, MBP, GALR1 and lOC284276." (PMID 36123715, 2022).
triple-negative breast carcinoma (1 paper, 2017). An invasive breast carcinoma which is negative for expression of estrogen receptor (ER), progesterone receptor (PR), and human epidermal growth factor receptor 2 (HER2). "We then collected 20 samples of triple-negative breast cancer paired with adjacent normal mammary tissues and analyzed by western blotting for the expression of ZNF516 and EGFR." (PMID 28947780, 2017).
cancer (4 papers, 2017 to 2024). A tumor composed of atypical neoplastic, often pleomorphic cells that invade other tissues. "The cancer genome atlas (TCGA) analysis showed that the ZNF516 gene is highly expressed in certain cancer types and is a potential suppressor of EGFR, which is related to breast carcinogenesis." (PMID 33750298, 2021). "As a result, multiple tumor suppressor genes, such as zinc finger protein 516 (ZNF516), membrane-associated guanylate kinase 1(MAGI1), SOCS1/2, TXNIP and VHL, are down-regulated, ultimately promoting cancer development and disrupting cellular metabolism and homeostasis." (PMID 38741782, 2024).
tumor (3 papers, 2017 to 2021). "We found that the protein levels of ZNF516 were lower in tumor samples than in adjacent tissues, whereas the levels of EGFR showed an inverse trend." (PMID 28947780, 2017). "There are limited studies of the tumor specific roles of HCFC2 and ZNF516, suggesting that additional studies are needed to elucidate their associations with LUAD." (PMID 33221751, 2020).
ZNF516 also shares sentences with these, for which no sentence is quoted: adenoma (1 paper); colorectal cancer (1).